CAT (catalase)
Diseases named in the same sentence as CAT in open-access papers (continued):
Sharing a sentence is not in itself a finding about the gene and the disease.
cancer (continued). "In addition, by combining this powerful H2O2 sensor with inhibitor‐base study, catalase, and gene interference techniques, our results demonstrated that the release of H2O2 after GLUT1‐mediated DHA stimulation induced dynamic redox disequilibrium in cancer cells." (PMID 37943018, 2023). "The catalase knock-down in BT-20-KD-CAT cells did not influence glutathione peroxidase activity, suggesting that glutathione peroxidase may not play a major role in protecting cancer cells against cytotoxic hydrogen peroxide." (PMID 22551313, 2012). "At the molecular level, significant upregulation of GPX4 and GSTA2 was observed in both cancer cell lines, whereas NFKB expression increased selectively in HT-29 cells, with no notable changes in CAT or SOD1 expression." (PMID 41745011, 2026). "Alpha-mangostin inhibited catalase activity in TNBC 4T1 cells but not antioxidant activity, resulting in the pro-oxidant effect on cancer cells." (PMID 38655233, 2023). "Caspase 3, Caspase 8, CAT, Bax and SOD genes expression increased compared to control (gene expression in cancer cells without any treatment)." (PMID 32295069, 2020). "Resveratrol-induced SOD2 expression was observed in cancer cells, although the expression of SOD1, CAT and GPX1 was not affected." (PMID 32316674, 2020). "Another strategy developed by cancer cells in order to maintain peroxides within non-toxic levels is that of up-regulating scavenging enzymes, such as SOD and catalase, also involved in drug resistance." (PMID 27683112, 2016). "Without catalase mimetic ability to remove H2O2, CNPs actually increased the toxicity of radiotherapy in cancer cells due to an accumulation of ROS in the cell." (PMID 26097523, 2015). "In the presence of SOD and catalase, EGCG also induced significant anticancer activities, suggesting that the effects of EGCG on cancer cells are independent of ROS." (PMID 26135316, 2015). "While over-expression of catalase in mice extended the life span, a reduction in SOD activity increased oxidative stress and cancer incidence but did not accelerate aging in mice." (PMID 22253967, 2009). "While classical enzymes such as SOD, catalase, and GPx have been extensively studied, other, non-classical oxidative stress-related enzymes (OSRE) may play critical roles in cancer progression." (PMID 39594421, 2024). "However, data on effects of the simultaneous expression of CAT and SOD1 on cancer promotion are not available." (PMID 36552527, 2022). "Thus, to counteract cell harm induced by ROS, an animal has numerous antioxidative barrier frameworks, including non-enzymatic (for the most part GSH) and enzymatic cancer prevention agent guards (counting SOD, GR, GST, CAT and GPx)." (PMID 28345375, 2017). "However, the protein levels and activity levels of catalase in this set of cancer cells were not significantly different from the non-tumorigenic cells studied, PANC-1 cells being an exception, which have higher levels of catalase activity than non-tumorigenic cells in this study." (PMID 38539894, 2024). "As for Nrf2, our results demonstrated an overexpression of SOD2 and CAT proteins in MPM cells and not in the mesothelium, thus confirm also for this factor its strong involvement in MPM resistance against oxidative stress and its overexpression in cancer cells." (PMID 33799965, 2021).
infection (519 papers, 2003 to 2026). The state of being infected such as from the introduction of a foreign agent such as serum, vaccine, antigenic substance or organism. "This decrease has been documented in prior studies, emphasizing a consistent pattern wherein CAT activity diminishes significantly during infections caused by P. berghei and P. vivax." (PMID 41001420, 2025). "PsCAT1, a monofunctional heme‐containing catalase secreted by Puccinia striiformis, acts as an important pathogenic factor to facilitate the infection of P. striiformis by scavenging host‐derived H2O2." (PMID 39254175, 2024). "It is possible that increased proteolysis, which is induced during the infection process, is the cause of the decrease in CAT activity in susceptible rice genotypes." (PMID 38635807, 2024). "In the earliest stages of infection, at 45 min, the enrichment analysis detected the term “response to chemical” which contained the stress-related catalase-encoding gene, CAT1, and the thioredoxin-encoding gene, TRR1." (PMID 38427950, 2024). "The infection caused by ToLCNDV-potato results in a notable increase in catalase activity in both cultivars, namely Kufri Pukhraj and Kufri Bahar, by approximately 48% and 55%, respectively." (PMID 37507984, 2023). "Several antioxidant defense enzymes (peroxidase, superoxide dismutase, catalase, and polyphenol oxidase) have been associated with infection." (PMID 36030517, 2022). "The trend in CAT activity differed between the slightly and highly susceptible lines after infection." (PMID 33767270, 2021). "Some of these genes (Mg1860, Mg2724) were up-regulated after infection of resistant and susceptible plants (DEGs across) and only one gene (Mg705) sharing homology with a catalase, was considered a DEG-RvsS." (PMID 32784493, 2020). "malvae, a catalase-encoding gene was highly expressed in the necrotrophic phase of an infection of round-leaved mallow, Malva pusilla." (PMID 33096724, 2020). "In order to repair the damage caused by ROS in response to pathogen infection, plants enhance the activities of antioxidative enzymes, such as CAT, SOD, POD, and PPO." (PMID 30634907, 2019). "Three defense-related unigenes, peroxidase, superoxide dismutase and catalase showed high homology percentage and were selected to study their expression in resistant and susceptible cultivars during infection with Xanthomonascampestris pv." (PMID 28324416, 2015). "Additional genes with evidence for positive selection and possible roles in host infection include katG, which encodes a catalase." (PMID 19912661, 2009). "Overall results showed that the activity of antioxidant (MDA, SOD, GSH and CAT) in Se-adequate mice was significantly higher than that of Se-deficient mice following the infection of C.parvum." (PMID 19247447, 2009). "Neonatal rat cardiac myocytes were infected with different multiplicity of infections (MOIs) of adenovirus encoding catalase (AdCat)." (PMID 14647150, 2003). "Notably, the interaction effects between trypomastigote count, NO, MDA, and CAT also had an association with genotoxicity, suggesting oxidative DNA damage in response to infection severity." (PMID 39861027, 2025). "Low CAT activity at later stages of infection may have been associated with peroxisome destruction caused by the pathogen." (PMID 38256790, 2024). "Curcumin was observed to enhance the activities of antioxidant enzyme SOD, CAT, and GPx by upregulating the expression of Cu/Zn SOD, MnSOD, CAT, and GPx mRNA, which was associated with the Keap1/Nrf2 signaling pathway in grass carp following infection with Aeromonas hydrophila." (PMID 38666864, 2024). "Indeed, the action of CAT on nAChR provides an explanation not only for the occurrence of care-related infection but also for long-lasting multiple organ failure-associated myopathy." (PMID 36297613, 2022).
infection (continued). "We became particularly interested in the peroxide detoxification strategy employed by L. monocytogenes during infection when our previous work revealed that the single catalase (encoded by kat) produced by the bacterium is required for aerobic growth, but dispensable during infection." (PMID 34287055, 2021). "This suggests that the reduced CAT levels during infection may contribute to parasite-caused cardiac pathogenesis." (PMID 34113663, 2021). "However, kat is not required for intracellular replication in macrophages or for virulence in a murine model of infection, and catalase-deficient strains have been isolated from infected humans." (PMID 34287055, 2021). "hordei secretes a catalase to scavenge H2O2 at the infection site, and Ustilago maydis, the causal agent of corn smut, decreases ROS production in the host by secreting an inhibitor of peroxidases." (PMID 35251065, 2021). "Such a difference in CAT activity between erythrocytes (low) and other organs such as the lung (high) was also found by Benzer and Yilmaz as the effect of oxidation stress caused by infection." (PMID 33171823, 2020). "To identify the fungal enzyme responsible for neutralizing ROS at the infection front, we reanalysed F. graminearum genome‐encoded catalase and catalase‐peroxidase genes based on phylogenetic analysis, conserved protein domains and subcellular localization prediction." (PMID 30919582, 2019). "All pathogenic Leptospira strains contained genes encoding catalase, collagenase, TonB-hemin binding receptor, immunoglobulin-like protein B and sphingomyelinases, which all are confirmed as virulence markers during the early stage of infection." (PMID 30832578, 2019). "As the most important virulence factor of E. coli O157 is Stx2 and adhesin intimin; the role of other virulence factor such as enterohaemolysin, a serine protease (EspP) and catalase or peroxidase (KatP) in causing infection in human may be low." (PMID 30170562, 2018). "Moreover, it has been reported that PPE reduces the production of NO and MDA while hindering the infection-induced loss of catalase activity." (PMID 27422638, 2016). "The infection was also linked with a catalase activity which tended to be lower." (PMID 22448287, 2012). "The current findings indicate that infection by Fusarium oxysporum and Sclerotium rolfsii on chickpeas in biochar-amended soil (with and without biocontrol agents) significantly affected the synthesis levels of catalase and peroxidase, thereby alleviating stress caused by pathogen infection." (PMID 41450937, 2025). "Furthermore, increased CAT activity in resistant Duli may enhance the elimination of ROS caused by pathogen infection, providing additional cellular protection." (PMID 40507885, 2025). "The antioxidative enzymes including SOD, POD and CAT are essential for plants to counteract environmental stresses, and plant-associated fungi have been reported to generate or secrete a range of compounds that activate plant immunity against pathogen infection." (PMID 38572240, 2024). "These female offspring from converging parental pairs may differ in arbovirus susceptibility factors early in infection such as those that promote or regulate oxidative stress (e.g. antioxidant enzymes like catalase) leading to a slower viral replication rate in the midgut." (PMID 34117363, 2021). "Moreover, the regulation of H2O2 may occur in a fluctuating manner because the association-dissociation of GLO and CAT could take place dynamically and transiently in response to environmental stresses or stimuli, e.g., drought and pathogen infection." (PMID 34229625, 2021). "After R. solani infection, all treatment groups showed a significant increase in POD, SOD, and CAT activities relative to pre-infection levels." (PMID 41602752, 2026). "In host cells, Aq significantly decreases oxidative stress markers (H2O2, SOD, CAT) during infection, indicating a beneficial effect on host responses." (PMID 42205576, 2026).
infection (continued). "Biochemical assays showed that wild-type infection induced strong antioxidant enzyme activities (peroxidase, catalase, superoxide dismutase), whereas these responses were attenuated under VeA silencing, corresponding to reduced oxidative stress." (PMID 42033050, 2026). "Compared with the 0 h time point, infection with A. veronii significantly increased the activity of CAT in the hepatopancreas of red claw crayfish at specific time points across different R. mucilaginosa dosage groups." (PMID 40646810, 2025). "In the current study, the measured GSH–Px and catalase serum activities indicated the oxidative stress in C. parvum infected mice suggesting its exaggeration in response to infection." (PMID 40029925, 2025). "Previous studies have indicated that plants exhibiting high expression of the MiPR1A gene show enhanced activities of antioxidant enzymes (SOD, POD, and CAT), conferring increased resistance to infections by C. gloeosporioides." (PMID 40507885, 2025). "The catalase activity of mycelia has been shown to increase under various stress situations, including pathogen infection, to maintain redox balance, resulting in resistance to environmental stress." (PMID 40985431, 2025). "The CAT activity of kidney tissues showed a complete trend of first increasing and then decreasing, reaching the highest level 24 h after infection, which was 0.85 times higher than the control group (P < 0.01)." (PMID 41401162, 2025). "The CAT activity in OE leaves was significantly higher than that in the control, peaking at 20 days post-infection." (PMID 41304614, 2025). "This indicates that the upregulation of CAT enzyme activity post-infection plays a crucial role in the degradation of H2O2, thereby bolstering the plant’s defensive mechanisms." (PMID 40507885, 2025). "In the cultivars Kaz10 and Zhnitsa with compatible interactions, infection with the S. nodorum SnB isolate led to an increase in CAT activity at 6, 24, and 72 hpi." (PMID 39942917, 2025). "The increased activities of SOD, POD, and CAT in GmCML-overexpressing lines suggest that this protein helps maintain optimal ROS balance during infection." (PMID 41157779, 2025). "The presence of catalase (5 μMMnP ethyl + 3 mM Asc + Cat) resulted in a similar number of amastigotes/macrophageand degree of infection, and ca. 7% increase in theinfection index compared to the untreated control." (PMID 41073350, 2025). "In the context of elevated oxidative activity during E. labbeana-like infections, such as impaired CAT function, can exacerbate H2O2-mediated tissue damage." (PMID 41278479, 2025). "The CAT activity of the liver tissues was 0.16 times higher than that of the control group at 24 h after infection, and it went down for (48 ~ 72h) before going up a little at 120 h." (PMID 41401162, 2025). "Field dodder infection led to increased activity of enzymes involved in scavenging reactive oxygen species, including catalase, guaiacol peroxidase, superoxide dismutase, and lipoxygenase in sugar beet." (PMID 40166631, 2025). "The activities of SOD and CAT showed a trend of first increasing and then decreasing with the extension of infection time, but they were generally higher than those of the control group." (PMID 41401162, 2025). "In order to detect the oxidation damage of EBL cells caused by M. bovis infection, the contents of catalase (CAT), superoxide dismutase (SOD), lactate dehydrogenase (LDH), and ROS levels in EBL cells after infection with M. bovis were determined." (PMID 39859536, 2025). "In the jejunum of infected mice, catalase enzyme activity was considerably diminished (p < 0.01) following infection with E. papillata." (PMID 41357758, 2025). "Naïve fish exhibited increased CAT activity following infection, whereas vaccinated fish experienced a transient decrease at 4 hpi, leading to significantly lower CAT activity at that time compared to naïve fish." (PMID 41256851, 2025).
infection (continued). "Biochemically, these transcriptional changes were mirrored by a sustained oxidative response, with elevated H2O2, peroxidase, catalase, and phenolic content throughout infection." (PMID 41348951, 2025). "In the STEC O157:H7 strain EDL933, ClpV mediates the translocation of catalase into macrophages, promoting immune evasion; notably, deletion of clpV reduces lethality in murine infection models." (PMID 41142573, 2025). "In this study, there were significant increases in SOD and CAT activities in R. dybowskii’s liver, spleen, and kidney from 6 to 120 h during Ah infection." (PMID 41401162, 2025). "Meanwhile, the activities of antioxidant enzymes such as SOD and CAT in the hepatopancreas are significantly enhanced, which can effectively scavenge excessive reactive oxygen species (ROS) induced by pathogen infection and alleviate oxidative stress damage." (PMID 40646810, 2025). "Following pathogen infection, the materials exhibited divergent response patterns: at 2 dpi, HT2 clustered with soluble sugars, total chlorophyll, Chl b, and CAT, while GT2 remained associated primarily with SOD activity." (PMID 40726552, 2025). "Our research findings indicate that CAT activity is decreased in all treatments compared to POD activity at the site of infection." (PMID 41450937, 2025). "To test this idea, we analyzed the expression of three marker genes for ROS during infection by TuMV, including CAT, GST and APX which encode catalase, glutathione S‐transferase and ascorbate peroxidase, respectively." (PMID 39532690, 2025). "Our results also show high expression of the catalase gene after 144 h of infection, likely reflecting a response to host-derived oxidative stress, as reactive oxygen species (ROS) such as hydrogen peroxide (H2O2) are produced to combat pathogens." (PMID 40611938, 2025). "Both, INO + AZA and INO + MEF treatments effectively enhanced CAT activity in stages of infection (3 dpi), but this was followed by a decreased at 9 and 21 dpi, suggesting a strong but not maintained initial activation of the antioxidant system." (PMID 41304631, 2025). "Key antioxidant enzymes (SOD, POD, CAT) constitute frontline defenses against biotic stress, with activity modulations quantitatively reflecting infection severity." (PMID 40333089, 2025). "The results show that following the infection, the activities of all the enzymes in transgenic plants were significantly boosted in comparison with NT plants, with CAT being the most inducible by pathogen infection." (PMID 39795373, 2025). "In the non-transgenic cerebellar cortex, peroxisome abundance remained unchanged, but catalase abundances decreased in granule (3.7-fold) and in Purkinje (3.8-fold) neurons of the cerebellar cortex after BoDV1 infection of TNFTg mice." (PMID 38339126, 2024). "Compared to 0 d, the activities of SOD, POD, and CAT after 5 d of infection increased by 47.8%, 71.3%, and 152.3%, respectively." (PMID 38658831, 2024). "Under Xa infection alone, CAT activities decreased, ranging from 11% to 31%, and the expression levels of ScCAT decreased from 20% to 44% in the four tested cultivars at 24 hpt compared with 0 hpt." (PMID 38592879, 2024). "Present results of increase in CAT activities by pathogen infection are in agreement with previous studies." (PMID 39480774, 2024). "Catalase activity increased after infection with the pathogen and the tolerant genotype showed more catalase activity." (PMID 39211839, 2024). "Most of the transcripts are highly expressed during infection and showed a significant upregulation in response to peroxide products compared to the nematode catalase enzymes." (PMID 38337937, 2024). "Specifically, during the early stage of infection in the incompatible interaction, CAT expression was found to be downregulated compared to the compatible interaction." (PMID 39365760, 2024).